GLIS2 (GLIS family zinc finger 2)
Diseases named in the same sentence as GLIS2 in open-access papers (continued):
Sharing a sentence is not in itself a finding about the gene and the disease.
tumor (11 papers, 2015 to 2025). "RNA-seq analysis of the tumor biopsy material confirmed the expression of the CBFA2T3::GLIS2 fusion transcript, with its sequence fully matching that obtained in the initial RNA-seq results." (PMID 40565358, 2025). "The results showed that GLIS2 expression in HCT116 enhanced the tumor number, weight and volume in xenograft experiment." (PMID 32483180, 2020). "As the host gene of circGLIS2, GLIS2 plays the role of a transcription factor and may act as an oncogene or tumor suppressor depending on the cell circumstances." (PMID 32968054, 2020). "Functional rescue experiments confirmed that BGN overexpression reverses the inhibitory effects of GLIS2 knockdown, while the Wnt/β-catenin inhibitor XAV-939 effectively blocks BGN's tumor-promoting effects." (PMID 40936440, 2025). "To further validate the key role of GLIS2 in tumors, we also compared the tumorigenic capacity of GLIS2Cter-expressing and CTL HMLER shEcad cells in orthotopic tumor implantation experiments." (PMID 34705506, 2021). "It has been previously demonstrated that the TP63/TP53L, ERG, GRHL1/Get-, HNF1A/TCF-1, SPI1/PU.1, WT1 and GLIS2, FOXM1 and FOXP3 transcription factor networks, which are mediated by HNF4A, can regulate the expression of Trop2 in tumor tissues." (PMID 25779928, 2015). "A FISH study of intraosseous tumor dabs revealed CBFA2T3::GLIS2 fusion formation and the absence of EWSR1 rearrangement." (PMID 40565358, 2025). "Comparison of the laBCC tumours before systemic treatment with localised BCC tumours yielded a significant differential expression of three genes of the Hh pathway: GAS1, GLI similar 2 (GLIS2), and protein kinase CAMP-activated catalytic subunit gamma (PRKACG) (P < 0.05)." (PMID 31988301, 2020). "In our research, we concluded that GLIS2 gene might be an effective molecular marker which was independent of tumor clinical indicators and an indicator of prognostic assessment indexes, which was consistent with the conclusion of previous study." (PMID 31281358, 2019).
GLIS2 also shares sentences with these, for which no sentence is quoted: chronic kidney disease (3 papers); infection (3); Bardet-Biedl syndrome (2); Megakaryoblastic Leukemia (2); melanoma (2); Renal atrophy (2); acute promyelocytic leukemia (1); bladder cancer (1); brain cancer (1); cervix cancer (1); diabetes (1); embryonal rhabdomyosarcoma (1); hepatocellular carcinoma (1); Hypertension (1); Insulin resistance (1); kidney disease (1); malakoplakia (1); Myelodysplasia (1); nonalcoholic steatohepatitis (1); Obesity (1); pancreas cancer (1); papillary thyroid carcinoma (1); psoriasis (1); renal failure (1); retinitis pigmentosa (1).